GATA2 (GATA binding protein 2)
Diseases named in the same sentence as GATA2 in open-access papers (continued):
Sharing a sentence is not in itself a finding about the gene and the disease.
neuroblastoma (continued). "Although GATA-2 and -3 expression has previously been described in various neuroblastoma cell lines, we show their expression in primary neuroblastoma for the first time." (PMID 19707195, 2009). "Multiple germline variants in GATA2 predispose individuals to familial myelodysplastic/acute leukemia syndrome, while germline GPC3 variants are observed in Simpson-Golabi-Behmel syndrome, an overgrowth syndrome that increases the risk of developing Wilms tumor, hepatoblastoma, and neuroblastoma." (PMID 37461096, 2023). "Since GATA2 and GATA3 are both involved in a complex transcription factor network regulating sympathoadrenergic traits, the frequent occurrence of super-enhancers in GATA2 and GATA3 loci appears to underlie the sympathetic noradrenergic cell identity of neuroblastoma cells." (PMID 33803938, 2021). "A recent study has shown that several master regulators important in sympathoadrenal neural crest lineages, including PHOX2A/B, GATA2/3, HAND2, SOX4/11, and INSM112 form a CRC on which the neuroblastoma tumor cells are dependent for survival and growth." (PMID 38653778, 2024). "Increased expression of CHGA, GATA2, and TBX2 was observed with STM2457 treatment in the neuroblastoma xenografts." (PMID 38691450, 2024). "While expression of GATA2 and GATA3 in human neuroblastoma with relatively low malignant potential has been previously reported, their functional roles in neuroblastomas have not been assessed." (PMID 33803938, 2021). "A better understanding of how GATA2 and GATA3 function as oncogenes or tumor suppressors is of prime importance for the treatment of neuroblastoma and urothelial cancers and will shed further light on their roles as prognostic factors." (PMID 33803938, 2021). "Identification of direct target genes regulated by GATA2 and/or GATA3 for neuroblastoma proliferation has become increasingly important." (PMID 33803938, 2021). "The observation of concordant expression of Gata-2, -3 and Fog-2 in the ganglia of neural crest origin, migrating neural crest cells (Fog-2) and favourable neuroblastoma supports the hypothesis that developmental molecular pathways are intact in this subtype of neuroblastoma." (PMID 19707195, 2009). "In contrast, GATA-2, -3 and FOG-2 are preferentially expressed in neuroblastomas with favourable prognostic characteristics." (PMID 19707195, 2009). "GATA-2, -3 and -4 and their cofactor friend-of-GATA (FOG)-2 were investigated in primary neuroblastoma by immunohistochemistry, real-time RT-PCR (n=73) and microarray analysis (n=251)." (PMID 19707195, 2009). "In this study, we characterise the expression patterns of GATA-2, -3, -4 and FOG-2 in murine nervous system development and primary human neuroblastoma to elucidate their potential implication in neuroblastoma pathogenesis." (PMID 19707195, 2009). "To quantify expression levels of GATA-2, -3, -4 and FOG-2 in various subtypes of neuroblastoma, we evaluated their mRNA levels." (PMID 19707195, 2009). "Published chromatin immunoprecipitation sequencing (ChIP-seq) experiments in neuroblastoma lines show binding of GATA2 and GATA3 to cRE1 and cRE3, but not cRE2 1,32." (PMID 37386251, 2023). "Furthermore, it is conceivable that GATA2 and GATA3 play a fundamental role in the genesis of neuroblastoma, given their roles in normal sympathoadrenal development." (PMID 33803938, 2021). "Using northern-blot analysis, consistent GATA-2, -3 and FOG-2 expressions were observed in tumours of lower stages (n=11), whereas a remarkable reduction in mRNA levels of all three genes was found in neuroblastoma of stage 4 (n=3)." (PMID 19707195, 2009). "As GATA transcription factors are involved in both tumourigenesis and SNS development, we aimed at characterising the expression patterns of GATA-2, -3, -4 and FOG-2 in primary human neuroblastoma and in neuronal development of mice to evaluate their possible implication in human neuroblastoma." (PMID 19707195, 2009).
neuroblastoma (continued). "In addition, Gata-2 overexpression arrested the proliferation of mouse neuroblastoma cells (NB2a), yet without induction of differentiation." (PMID 19707195, 2009). "However, the functional role of GATA2 in neuroblastoma has not been fully studied." (PMID 36980710, 2023). "The transcription factors GATA-2 and -3, which are essential for normal SNS development, and their cofactor FOG-2 are downregulated in aggressive but not in favourable neuroblastoma." (PMID 19707195, 2009).
lung carcinoma (17 papers, 2015 to 2025). "GATA2 expression promotes inflammation in the whole body and various tissues, including mast cells, vascular endothelial cells, lung cancer, and kidneys." (PMID 40516868, 2025). "Meanwhile, there is plenty of evidence that SMAD9, ITIH4 and GATA2 have close connection with the initiation, progression and prognosis of various malignancies including lung cancer." (PMID 33648465, 2021). "In lung cancer, GATA2 and GATA6 were significantly downregulated genes in 17 and 15 studies, respectively." (PMID 30872657, 2019). "Recently, evidence from studies of aplastic anemia, MonoMAC syndrome, and lung cancer has demonstrated a mechanistic link between GATA-2 and human pathophysiology." (PMID 26325290, 2015). "The zinc finger-containing transcriptional regulator GATA2 serves as a pivotal mediator of hematopoiesis regulation and cellular homeostasis, has been shown in multiple studies to exhibit significantly reduced expression in lung cancer." (PMID 40647501, 2025). "On the contrary, levels of GATA2 were upregulated in two lung cancer cell lines." (PMID 34093794, 2021). "Given the pathophysiological links between GATA-2 and aplastic anemia, MonoMAC syndrome, and lung cancer, it is extremely important to clarify and comprehensively understand the details regarding the mechanisms behind the upstream transcription of GATA-2." (PMID 26325290, 2015). "GATA2, a transcription factor directly known to regulate the IL-1β signaling pathway, has been shown to function as a link between IL-1β signaling and tumor cell proliferation, since GATA2 genetic depletion diminishes tumor burden and progression in K-ras-induced lung cancer models." (PMID 32039025, 2019). "FERMT2 together with FKBP3, SMAD9, GATA2, and ITIH4 was constructed as a prognostic signature of lung cancer based on the differential expression of immune genes." (PMID 36253873, 2022). "The aberrant expression or DNA modification of GATA-2, GATA-4, GATA-5, and GATA-6 was found in lung cancer, but GATA-1 gene expression is seldom reported in LADC." (PMID 29100282, 2017). "Co-expression network construct indicated that some of the mostly connected mRNAs and TFs were previously reported to be dysregulated in lung cancer, including SOX2, FOXF1, PTK2B, XRCC2, AML-1a (RUNX1), GATA-2 and MZF1." (PMID 26159226, 2015). "GATA2 was significantly downregulated in both human and mouse lung tumors and its further suppression was not an effective treatment for KRAS mutant lung cancer." (PMID 34093794, 2021). "However, the relationship between GATA2 or GATA1 and the clinical and prognosis of lung cancer has not been clarified." (PMID 34093794, 2021). "For example, the expression of GATA2 in human and mouse lung tumors were distinctly downregulated compared with normal lung tissues and its further suppression was not an effective treatment for KRAS mutant lung cancer 12, while GATA2 was essential for survival of KRAS mutant NSCLC cells." (PMID 34093794, 2021).
Myelodysplasia (17 papers, 2014 to 2026). Clonal hematopoietic stem cell disorders characterized by dysplasia (ineffective production) in one or more hematopoietic cell lineages, leading to anemia and cytopenia. "It is important to note that a myeloablative conditioning regimen followed by HSCT is the standard approach in pediatric patients with myelodysplasia, particularly in patients with high-risk features such as monosomy 7 (often found in patients with GATA2 related MDS)." (PMID 33066218, 2020). "AML with myelodysplasia‐related changes, GATA2, and MLLT10 abnormalities were detected in other six patients, respectively." (PMID 35847688, 2020).
pulmonary alveolar proteinosis (16 papers, 2015 to 2025). A rare lung disorder characterized by the filling of the pulmonary alveoli with proteinaceous material which stains positive with periodic acid-Schiff stain. "GATA2 deficiency is also associated with extra-hematologic manifestations, including sensorineural hearing loss and pulmonary alveolar proteinosis." (PMID 40981111, 2025). "GATA2 deficiency is also associated with extra-hematologic manifestations, including sensorineural hearing loss, pulmonary alveolar proteinosis, and increased susceptibility to atypical mycobacterial infections, all of which warrant long-term surveillance." (PMID 40981111, 2025). "In humans, defective GM-CSF signaling impairs the capacity of lung macrophages to consume surfactant, causing pulmonary alveolar proteinosis, a severe GATA2 deficiency syndrome phenotype." (PMID 36809258, 2023). "Since reduced GM-CSF signaling causes pulmonary alveolar proteinosis, a GATA2 deficiency syndrome phenotype, we analyzed the underlying mechanism." (PMID 36809258, 2023). "As patients with anti-GM-CSF antibodies or with genetic defects on the GM-CSF pathway like GATA-2 deficiency, present severe lung involvement such as pulmonary alveolar proteinosis, the GM-CSF MDM is generally considered the most relevant model to simulate human AM in vitro." (PMID 29562615, 2018). "P01 received a myeloablative allogeneic HCT due to progressive lung dysfunction caused by pulmonary alveolar proteinosis (PAP), a well-described GATA2 deficiency-associated complication caused by dysfunctional alveolar macrophages." (PMID 36268026, 2022). "Noninfectious pneumonia is seen in adenosine deaminase (ADA) deficiency and pulmonary alveolar proteinosis (due to CSF2RA and GATA2 deficiency)." (PMID 37102642, 2023). "Pulmonary involvement is increasingly reported in patients with GATA2 mutations, ranging from opportunistic infections to interstitial lung disease and pulmonary alveolar proteinosis, even in the absence of overt hematopoietic dysfunction." (PMID 41438140, 2025).
primary immunodeficiency (15 papers, 2016 to 2025). "Overall, in our study, primary immunodeficiencies, including GATA2 deficiency, were identified as the predominant factor, accounting for 12.9% of germline predispositions in young-onset MDS patients." (PMID 38137719, 2023). "GATA2 deficiency is a rare primary immunodeficiency that has become increasingly recognized due to improved molecular diagnostics and clinical awareness." (PMID 34893945, 2022). "Primary immunodeficiency induced by GATA2‐deficiency might have played a major role in the development of MCC, supporting a possible association between GATA2–deficiency and MCC." (PMID 39614632, 2024). "Though T cell immunity is clearly important for anti-mycobacterial defense, myeloid cells are also essential, as demonstrated by many forms of primary immunodeficiency such as GATA2 haploinsufficiency, IFNGR1/2 deficiency, Chronic granulomatous disease, and IRF8 deficiency." (PMID 30984189, 2019). "Germline mutations leading to haploinsufficiency of Guanin-adenine-thymine-adenine 2 binding protein (GATA2) represent the underlying cause of a disorder encompassing primary immunodeficiency (PID), hematological malignancies and vascular/lymphatic abnormalities." (PMID 30564229, 2018). "GATA Binding Protein 2 (GATA2) haploinsufficiency is an autosomal dominant or sporadically inherited primary immunodeficiency first genetically described in 2011." (PMID 39267745, 2024). "Primary immunodeficiency, such as is associated with EVER1, EVER2, GATA2, CXCR4, and DOCK8 mutations, as well as combined immunodeficiency, such as in bare lymphocyte syndrome, is associated with extensive HPV infection." (PMID 38637854, 2024). "Here we described another 28-year-old man with a GATA2 variant who also suffered from hemophagocytic lymphohistiocytosis(HLH), who was finally diagnosed with HLH triggered by Mycobacterium avium bloodstream infection due to primary immunodeficiency." (PMID 37680631, 2023). "The importance of GATA2 in myelopoiesis is illustrated by patients with inactivating mutations in GATA2, many of whom develop MonoMAC syndrome, a primary immunodeficiency characterized by a near absence of circulating myeloid, NK and B cells." (PMID 33193444, 2020). "This is the first report of VZV-triggered HLH-like disease in a primary immunodeficiency and the third report of HLH in GATA2-haploinsufficiency." (PMID 30564229, 2018). "We report a novel primary immunodeficiency, and a differential molecular diagnosis to CXCR4‐,DOCK8‐,GATA2‐,MAGT1‐,MCM4‐,STK4‐,RHOH‐,TMC6‐, and TMC8‐related diseases." (PMID 27896283, 2016).
endometriosis (13 papers, 2014 to 2024). The growth of functional endometrial tissue in anatomic sites outside the uterine body. "Several studies have reported elevated levels of GATA6 concomitant with loss of GATA2 in endometriosis." (PMID 39443360, 2024). "Work in pre-clinical models implicates epigenetic silencing of GATA2 in endometriosis pathogenesis, whereupon loss of GATA2 expression blunts hormone-dependent transcriptional pathways that contribute to endometriosis pathology." (PMID 39443360, 2024). "Aberrant GATA2 expression has been linked to common endometrial disorders including endometriosis." (PMID 39443360, 2024). "Our findings support loss of GATA2 and PGR autoregulation in EAH/EIN and endometriosis, and suggest that loss of GATA2 in stromal cells may reliably separate these lesions from normal endometrial tissues." (PMID 39443360, 2024). "Our findings indicate that GATA2 dysregulation is a feature of endometriosis and EAH/EIN, and support a model whereby loss of stromal GATA2 in these disorders contributes to their progesterone insensitivity." (PMID 39443360, 2024). "When we stratified benign endometrium and endometriosis cases by menstrual phase, GATA2 expression in the glands and stroma was significantly different in proliferative but not secretory phase." (PMID 39443360, 2024). "It would also be interesting to define GATA2 patterns and expression levels in endometriosis and EAH/EIN following treatment with progestin therapy." (PMID 39443360, 2024). "The number of GATA2 positive glandular cells in endometriosis lesions was similar to normal secretory endometrium and significantly less than normal proliferating endometrium." (PMID 39443360, 2024). "Although overall GATA2 levels are preserved in the glandular cells of endometriosis, GATA2 expression is decoupled from PGR levels, suggesting that PGR-independent pathways regulate GATA2 expression in these cells." (PMID 39443360, 2024). "In human endometrial stromal cells, silencing of GATA2, diminishes markers of decidualization and interestingly the expression level is significantly reduced in the endometrium of women with endometriosis." (PMID 36387918, 2022). "The GATA2 was found to be unmethylated and abundant in stromal cells of eutopic endometrium, but methylated and inactive in stromal cells of endometriosis." (PMID 36612107, 2022). "In endometriosis, there appears to be a switch from a GATA2 driven P4-responsive state to a GATA6-driven P4-resistant state based on CpG methylation patterns." (PMID 31387263, 2019). "GATA6, which is hypomethylated and abundant in endometriotic cells, potently blocked hormone sensitivity, repressed GATA2, and induced markers of endometriosis when expressed in healthy endometrial cells." (PMID 24603652, 2014). "Interestingly, even though glandular GATA2 expression was similar to secretory endometrium controls, GATA2 expression correlated with PGR in benign endometrium whereas this relationship was lost in endometriosis." (PMID 39443360, 2024). "Performing regular aerobic exercise with vitamin B6 consumption may decrease GATA2 gene expression levels of endometriosis in model rat." (PMID 37260552, 2023). "Finally, we sought to determine whether GATA2 depletion may promote extension of endometriosis lesions towards extra-uterine sites." (PMID 39443360, 2024). "Although average glandular GATA2 expression was preserved in endometriosis and EAH/EIN cases, its expression was decoupled from PGR, implying that alternative pathways regulate GATA2 levels in these disorders." (PMID 39443360, 2024). "We further correlated the relationship between GATA2 and PGR on a case-by-case basis in endometriosis." (PMID 39443360, 2024). "Our results show a strong coupling of GATA2 and PGR expression levels in the stromal and glandular elements of normal endometrium, which is lost in endometriosis and EAH/EIN." (PMID 39443360, 2024).
endometriosis (continued). "Other transcriptional factors involved in regulation and mediation of progesterone signaling (IGFBP1, GATA2, FOXO1, ARID1A, NOTCH1and WNT4), required for successful implantation are also reduced in endometrium of women with endometriosis." (PMID 36387918, 2022). "The epigenetic regulation (DNA methylation) of genes GATA2 and GATA6 has been noticed in endometriosis." (PMID 36612107, 2022). "Epigenetic changes in these genes, with downregulation and hypermethylation of GATA2 and hypomethylation and activation of GATA6, have been postulated to be involved in progesterone resistance and altered estrogen responses in endometriosis." (PMID 28125717, 2017). "We find that while GATA2 expression is lost in the stromal cells of endometriosis and EAH/EIN, we detect no corresponding increase in GATA6." (PMID 39443360, 2024). "This reduction in GATA2 expression does not lead to a detectable increase in GATA6 expression in endometriosis." (PMID 39443360, 2024). "We scored GATA2, GATA6, and PGR IHC in endometriosis biopsies from 18 patients." (PMID 39443360, 2024). "GATA2 also has PGR-independent functions that maintain endometrial cell identity, and GATA2 transcripts reportedly are down-regulated in endometrial disorders including endometriosis." (PMID 39443360, 2024). "GATA2 expression is markedly reduced in stromal but not glandular cells in endometriosis and EAH/EIN." (PMID 39443360, 2024). "Moreover, we suggest that GATA2 and GATA6, as target TFs of the miR-200 family, might be involved in the pathogenesis of endometriosis together with the miR-200 family." (PMID 29357938, 2018).